MIR6802 (microRNA 6802)
Synonyms: hsa-mir-6802
Gene: MicroRNA gene on chromosome 19 (55,239,912 to 55,239,976, reverse strand). Ensembl gene ENSG00000278328.
Homologues: Orthologues: chimpanzee MIR6802 (100% identical).